BRCA1 (BRCA1 DNA repair associated)
Diseases named in the same sentence as BRCA1 in open-access papers (continued):
Sharing a sentence is not in itself a finding about the gene and the disease.
breast cancer (continued). "In breast cancer, POU4F2 can repress BRCA1 expression and interact with estrogen receptor alpha to enhance its activity." (PMID 27923066, 2016). "Aberrant methylation patterns were reported for e.g. the BRCA1 promoter and the tumour suppressor RASSF1A in breast cancer." (PMID 26927176, 2016). "This is further exemplified by use of PARP inhibitors to exploit the DNA repair defect of BRCA1 and BRCA2 mutant breast cancers." (PMID 26943587, 2016). "To verify this finding, we performed BRCA1 knockdown experiments using two different siRNAs on MCF10A and the luminal breast cancer cell line MCF7, which both express wild-type BRCA1." (PMID 27556296, 2016). "Here we evaluated the anti-proliferative activity of 198 FDA-approved and experimental drugs against four BRCA1-mutant (HCC1937, MDA-MB-436, SUM1315MO2, and SUM149PT) and four BRCA1-wild-type (MDA-MB-231, SUM229PE, MCF10A, and MCF7) breast cancer cell lines." (PMID 27313062, 2016). "The fact that breast cancer development in BRCA1-mutation carriers is crucially affected by female sex hormones led to the question whether RANK/RANKL, which are key molecules in the mammary gland downstream of steroid hormones, have a role in the aetiology of BRCA1 mutation-driven breast cancer." (PMID 27881737, 2016). "While BRCA1 and BRCA2 mutations affect a minority of breast cancer patients (fewer than 5%), BRCA1 and BRCA2 were silenced by promoter region hypermethylation in 9% and 2% of sporadic breast cancer, respectively." (PMID 26967246, 2016). "Indeed, our previous study have revealed among 40 breast cancer patients, at increased risk of carrying a mutation, 29 women with negative BRCA1/2 testing and 11 patients with a positive BRCA1/2 status including six patients with BRCA1 mutation and five patients carrying BRCA2 mutation." (PMID 27129401, 2016). "A similar link was also observed between the CD44+/24–/low profile and BRCA1 expression status in basal–like breast cancer cells, as HCC1937 expressed higher CD44+/24–/low cells than the HCC1937/wt BRCA1 cell line." (PMID 27229859, 2016). "However, the roles of lncRNAs in BRCA1-related breast cancer remain largely unknown." (PMID 27556296, 2016). "Because of the critical role of FOXC1 in BLBC cell function, along with an opposing expression pattern between BRCA1- and BRCA2-mutant breast cancers, it is speculated that BRCA1, not BRCA2, mutation-elicited signaling might synergize with FOXC1 action in mammary tumorigenesis." (PMID 27708239, 2016). "Interestingly, epidemiological studies suggest that early pregnancies do not confer reduced breast cancer risk in women carrying a BRCA1 mutation, but might even elevate cancer incidence." (PMID 27881737, 2016). "We report findings that further support the involvement of ovarian hormones in BRCA1-related tumor development and support the use of SPRM treatment for breast cancer prevention." (PMID 27246982, 2016). "In wild-type sporadic breast cancer lines, AKT1 has been shown to promote cytoplasmic retention of BRCA1 and Rad51." (PMID 27465688, 2016). "In this study, BRCA1 mutation rate is identical to BRCA2 mutation rate; this result may be due to the small number of patients analyzed but if this finding is confirmed in elevated sample, the BRCA1/2 mutations may contribute similarly to early-onset breast cancer in Algeria." (PMID 26997744, 2016). "Several genes predisposing to breast cancer have been identified, including BRCA1 and BRCA2, which explain about 20% of the familial breast cancer cases." (PMID 27158822, 2016).
breast cancer (continued). "Since a small proportion of normal breast epithelial cells had BRCA1 methylation, our preliminary findings suggest that methylation of BRCA1 may be involved in breast tumors initiation and progression; therefore, it could be used as a biomarker for the early detection of sporadic breast cancer." (PMID 27413552, 2016). "Of note, the rates of TOP1 and CDH3 positivity were the highest in BRCA1-related breast carcinomas (48%) followed by BRCA2-related (24%) and sporadic breast carcinomas (7%)." (PMID 27566577, 2016). "Protein expression of CDH3 and TOP1 was analysed in a panel of 253 human breast carcinomas comprising 102 BRCA1-related, 49 BRCA2-related and 102 sporadic breast carcinomas." (PMID 27566577, 2016). "With regard to CDH3, a significant difference was found among the three groups with 76% of BRCA1-related, 37% of BRCA2-related and 22% of sporadic breast carcinomas being CDH3 positive (p < 0.001)." (PMID 27566577, 2016). "TOP1 overexpression was mostly observed in BRCA1-related (60%) and in BRCA2-related breast carcinomas (59%) as compared to sporadic breast carcinomas (35%)." (PMID 27566577, 2016). "For BRCA1 and BRCA2 there was a tendency towards a worse breast cancer-specific and overall survival, however, results were heterogeneous and the evidence was judged to be indecisive." (PMID 25816289, 2015). "However, the subtle nature of BRCA1 function and the well-known discrepancies between human and murine breast cancer biology and genetics may limit the utility of mouse systems in defining the function of BRCA1 in cancer and validating the development of novel therapeutics for breast cancer." (PMID 26379698, 2015). "Indeed, Molyneux and colleagues found that ERneg luminal progenitors, and not basal stem cells, when targeted with a Brca1 mutation in mice, can yield mammary tumors that closely resemble human BRCA1 mutant (basal-like) breast cancer, at least by histological examination." (PMID 25688859, 2015). "BRCA1 (breast cancer 1, early onset) has recently been identified as the 17th FANC gene and assigned the FANCS synonym." (PMID 26596371, 2015). "The PALB2 p.G998E variant in this patient was reported at a similar frequency of ~ 10% in a population of BRCA1- and BRCA2-negative male breast cancer patients in Northern Italy as was observed in healthy individuals." (PMID 26485759, 2015). "The expression of both PARP1 and BRCA1, both PARP1 and BRCA2, or both BRCA1 and BRCA2 in breast cancer were 17%, 22%, and 15%, respectively." (PMID 25865228, 2015). "Together, our results provide a mechanism for how BRCA1 regulates PIG3 expression and illustrate the relevance of this mechanism to clinical outcomes in breast cancer patients." (PMID 25797244, 2015). "It has been shown that both indole-3-carbinol and genistein induce the gene expression of BRCA1 in MCF-7 and T47D breast cancer cells." (PMID 25636033, 2015). "A few biomarkers such as BRCA1/2 and HER-2/neu have been very useful in guiding therapeutic interventions in breast cancer." (PMID 25798919, 2015). "Hence, the association of the BsmI SNP with: i) overall breast cancer risk, ii) breast cancer risk in BRCA1/2 non-carriers, and iii) breast cancer risk in BRCA1/2 non-carriers with a positive family history of breast and/or ovarian cancer, reached statistical significance." (PMID 26517870, 2015). "Then, we compared the effects of αNF on BRCA-1 and ERα expression in MCF-7 and UACC-3199 breast cancer cells." (PMID 26715507, 2015). "Recently, a renewed interest in platinum-based chemotherapy in breast cancer is observed, especially in the treatment of triple-negative (TNBC) and BRCA1/2-mutant tumors." (PMID 26580554, 2015). "Interestingly, the distribution of BRCA1, BRCA2 and ATM rare germline truncations with their somatic mutations across cancer types varies with the high frequency of ATM in prostate, lung and stomach cancers, and BRCA1 and BRCA2 germline events in ovarian and breast cancers." (PMID 26689913, 2015).
breast cancer (continued). "We note, however, that the analysis of both cohorts supports the observation that basal‐like breast cancers, regardless of whether or not they are Epi‐Basal, significantly associate with promoter methylation of the BRCA1 gene ‐ a central tumor suppressor gene in breast cancer (data no shown)." (PMID 25468711, 2015). "To this end we treated BRCA1 mutant (SUM-149PT) and BRCA2 mutant (HCC-1428) breast cancer cells with 2 μM AZD2281 for 1 day and stained them with acridine orange." (PMID 25975349, 2015). "We divided the 21 patient datasets into 3 breast cancer types: 12 sporadic (i.e., tumors WT/WT for both BRCA1 and BRCA2), 5 BRCA1, and 4 BRCA2 mutant tumors." (PMID 25699710, 2015). "Even well known driver oncogenes such as BRCA1 and BRCA2 have a relatively low prevalence (∼12%) in breast cancer populations." (PMID 26779250, 2015). "Twenty probes in the BRCA1 promoter region showed increased methylation in triple-negative breast cancers compared to Luminal A, Luminal B and HER2-positive breast cancer subtypes." (PMID 26438025, 2015). "The majority of hereditary OC (HOC) cases are also associated with an increased risk of breast cancer (BC) and the most frequent pathogenic mutations in hereditary breast and/or ovarian (HBOC) cancer families affect the BRCA1 gene and to a lesser extent also BRCA2." (PMID 26057125, 2015). "However, BRCA1/2 mutations do not account for all breast cancer susceptibility genes and there are other genetic factors, known and unknown that may play a role in the development of such disease." (PMID 25923920, 2015). "Amplification of TNRC9, a common event in breast cancer from the MENA region, can directly result in the epigenetic silencing of BRCA1 expression." (PMID 25951871, 2015). "This study is the first to report ERCC1, BRCA1 and SLCO1B3 as markers of response to NCT in breast cancer." (PMID 26180747, 2015). "AZD2281 induced significant autophagy (37 and 44%) in BRCA1 mutant SUM-149PT and BRCA2 mutant HCC-1428 breast cancer breast cancers, respectively, in 24 of treatment." (PMID 25975349, 2015). "The data involve variants in the coding and flanking intron sequences of the human BRCA1 and BRCA2 genes in Hispanic subjects with breast cancer." (PMID 26543556, 2015). "Tissue microarray analysis of 149 breast cancer patient samples revealed a positive correlation between PIG3 and BRCA1 expression (r = 0.678, P < 0.001)." (PMID 25797244, 2015). "With the availability of a three-tube multiplex for the complete BRCA1 and BRCA2 genes we sought to apply this approach to a cohort of Hispanic/Latin American breast cancer patients." (PMID 26543556, 2015). "Similar correlations between BRCA1 and FOXA1 expression were observed in a panel of breast cancer cell lines with different levels of wild-type BRCA1." (PMID 25531315, 2015). "In light of these findings, collectively, our results lead us to propose a mechanistic model in which BRCA1 can promote FOXA1 transcriptional expression and thereby, breast cancer luminal subtype development through targeting EZH2." (PMID 25531315, 2015). "Several studies have shown that the morphological and immunohistochemical phenotypes of BRCA1- and BRCA2-related breast cancers differ from that of sporadic breast cancers." (PMID 26496879, 2015). "To determine the prevalence and clinical significance of PARP1, BRCA1 and BRCA2 in breast cancer development, we investigated their expression in 110 cases of tissues and adjacent normal tissues by using immunohistochemistry." (PMID 25865228, 2015). "TN sporadic breast cancer tissues showed significantly higher expression level of miR-214 than TN hereditary individuals that are consistent with the finding in other study; miR-214 is expressed differentially in ovary cancer patients with and without the BRCA1 gene mutations." (PMID 25705321, 2015).
breast cancer (continued). "Perhaps the most convincing evidence is that downregulation of BRCA1 by UBE2T in breast cancer significantly promoted proliferation and tumor growth of breast cancer cells." (PMID 26308072, 2015). "In contrast to our BRCA1 profiling results, most of these CNAs in CHEK2*1100delC breast cancers are seen at very low frequencies and are marginally statistically significant." (PMID 26553136, 2015). "Compared to the BRCA1 and BRCA2 profiles reported in literature and our previous study, copy number aberrations are infrequently seen in CHEK2*1100delC breast cancers." (PMID 26553136, 2015). "Of a total 131 breast cancer sera analyzed, 15.3% (20/131) was shown to have autoantibody to PARP1, 19.1% (25/131) was shown to have autoantibody to BRCA1, 36.6% (48/131) was shown to BRCA2." (PMID 25865228, 2015). "In addition, BRCA1 may directly downregulate the AKT protein either by ubiquitin-mediated proteasomal degradation or by activating a protein serine/threonine phosphatase PP2A in breast cancer cells." (PMID 25426449, 2014). "Our laboratory identified BRCA1 as a regulator of ALDH+ CSCs, while a previous study showed that Xist RNA concentration in XCI was increased by BRCA1 in breast cancer cells, suggesting Xist regulation of breast CSCs is in a BRCA1 dependent manner." (PMID 26932376, 2014). "In breast cancer cells, MYC was found to directly regulate the BRCA1 promoter via binding to distal regulatory regions." (PMID 24624361, 2014). "However, according to MLPA analysis, one breast cancer patient was detected with an average intra normalized ratio (probe signal of each amplification product/ all reference probe signals within each sample run) of 0.64 in exon 6 of BRCA1 gene which was predicted as an ambiguous deletion." (PMID 24906410, 2014). "Our findings suggest a hypothesis where in women with the BRCA1-3’UTR-variant, if progressing to an estrogen independent phenotype, their BRCA1 becomes even less functional, possibly allowing more DNA damage, and perhaps selection for a more aggressive breast cancer genotype." (PMID 24915755, 2014). "Here, we describe an Italian family with a high number of cases of breast cancer and other types of tumour subjected to the MLPA test to verify the presence of BRCA1, BRCA2 and CHEK2 deletions and duplications." (PMID 24986639, 2014). "In breast cancer cells, HOXA9 has been shown to directly regulate BRCA1 expression and to suppress growth and survival." (PMID 24886209, 2014). "Moreover, our results show that, to a large extent, the differences in breast cancer associations of known breast cancer susceptibility loci between BRCA1 and BRCA2 carriers and the general population are due to differences in the prevalence of tumor subtypes in BRCA1 and BRCA2 carriers." (PMID 25919761, 2014). "In addition, there is little data on how systemic vitamin D status might interact with other known breast cancer risk factors including genetic (BRCA1, BRCA2, ATM), endocrine (estrogen, progesterone) and environmental (radiation, carcinogens) modulators of breast cancer development." (PMID 24982636, 2014). "BRCA1 and BRCA2 were predominantly methylated in breast cancer while p14 was more frequently methylated in oesophageal and colon cancer samples, ranging in frequency between 33.3% and 70%." (PMID 24607238, 2014).
breast cancer (continued). "Several recent studies on breast cancer stem-cells indicate altered regulation of DNA repair networks, particularly an inverse relationship between ALDH1A1 status and BRCA1 gene expression." (PMID 25216266, 2014). "Therefore, targeting the BRCA1 RING domain protein through the disruption of the BRCA1 E3 ligase activity by this class of ruthenium complexes might be an effective approach to eradicate breast cancers." (PMID 24507701, 2014). "BRCA1 is known to bind AhR and ARNT to activate the transcription of their target genes in breast cancer cells." (PMID 24704793, 2014). "Most notable are the discoveries of the BRCA1 and BRCA2 genes, identified in multiple-case family studies in which breast cancer cases were observed to follow a Mendelian pattern of inheritance." (PMID 25112280, 2014). "Due to these similarities, it has been hypothesized that the DNA repair defects that sensitize BRCA1-deficient breast cancer tumors to platinum may also be present in TNBC, indicating that platinum-based chemotherapies may be an effective treatment option for this subset of breast cancer." (PMID 24527094, 2014). "Consistent with this, treatment with an HSP90 inhibitor was shown to degrade and deplete expression of BRCA1, ATR and CHK1, resulting in impairment of the DDR and DNA repair, which sensitized breast cancer cells to DNA damage." (PMID 25026298, 2014). "While the role of BRCA1/2 defects has been well studied in TNBC, significantly less information is available for other breast cancer subtypes." (PMID 25475740, 2014). "Consistent with this, the siRNA-based BRCA1 knockdown (BRCA1-KD) enhanced both basal and the H2O2-mediated ROS production in one normal-like (MCF10A) and two breast cancer (MCF7 and T47D) cell lines." (PMID 24704793, 2014). "Our data indicated that lestaurtinib is a potent therapeutic agent for killing breast cancer cells and it amplifies the ability of the PARP1 inhibitor AG14361 to kill breast cancer cells irrespective to their BRCA1 status." (PMID 24962108, 2014). "In addition, it has been reported that BRCA1 expression was reduced or undetectable in the majority of high-grade, ductal carcinomas, suggesting that absence of BRCA1 may contribute to the pathogenesis of a significant percentage of sporadic breast cancers." (PMID 24171172, 2013). "Using anti-BRCA1 antibodies AP16 and K-18 on frozen sections we found punctate BRCA1 staining and more homogeneous staining with the MS110 antibody in variable numbers of tumor cell nuclei and nucleoli of breast cancer patients." (PMID 23855721, 2013). "In addition, the investigation of multiple mutants of BRCA1 from patients that disrupt the interaction of E2 enzymes without perturbing the BRCA1–BARD1 complex has revealed that E3 ligase activity strongly correlates with BRCA1 functions in HR, and breast cancer susceptibility." (PMID 23388117, 2013). "In this study, we investigated the expression of VEGF and HIF-1α and microvessel density (MVD) in 26 BRCA1-2 carriers and 58 BRCAX compared to 77 sporadic breast cancers, by immunohistochemistry." (PMID 23326384, 2013).